ENSG00000239005
Synonyms: LOC124900188
Gene: Small nucleolar RNA gene on chromosome 4 (139,436,368 to 139,436,494, reverse strand). Ensembl gene ENSG00000239005.
Gene Ontology:
Biological process: RNA processing
Cellular component: nucleolus
Homologues: Orthologues: mouse Snora78 (82% identical), rat LOC120095472 (80% identical). Paralogues in human: SNORA78 (91% identical).